MMP9 (matrix metallopeptidase 9)
Diseases named in the same sentence as MMP9 in open-access papers (continued):
Sharing a sentence is not in itself a finding about the gene and the disease.
staphylococcal pneumonia (1 paper, 2024). Pneumonia caused by infections with bacteria of the genus staphylococcus, usually with staphylococcus aureus. "Together with the observed enhanced MMP9 release as well as other epithelial factors involved in extracellular matrix remodeling, this may affect healing in staphylococcal pneumonia in STAT3 deficiency." (PMID 37982695, 2024).
Streptococcus pneumonia (1 paper, 2021). "Furthermore, antibiotic treatment might increase the expression of MMP-9, and antibiotics with dexamethasone could inhibit the expression of MMP-9 in rats with Streptococcus pneumonia." (PMID 33808027, 2021).
stress-related disorder (1 paper, 2025). Stress-related disorders are mental health disorders that are a result of an atypical response to both short and long-term anxiety due to physical, mental, or emotional stress. "Concerning stress-related disorders, both acute and chronic restraint stress increase MMP-9 activity in the hippocampus." (PMID 40894006, 2025).
T-cell acute lymphoblastic leukemia (1 paper, 2022). Acute lymphoblastic leukemia of T-cell origin. "In patients with T-cell acute lymphoblastic leukemia (T-ALL), HIF-1α is overexpressed, and HIF-1α can promote the activation of Notch1 signaling, increase the expression of cyclin D1, CDK2, p21, MMP2, and MMP9 proteins, thereby leading to cell proliferation, invasion, and resistance." (PMID 35684364, 2022).
T-cell leukemia (1 paper, 2021). A malignant disease of the T-lymphocytes in the bone marrow, thymus, and/or blood. "As a consequence, the overall structure remained intact and IL-7 cleaved by MMP-9 remained able to induce IL-7R internalization, to activate signal transduction through pSTAT3 and to induce cell proliferation in the human T cell leukemia cell line HPB-ALL." (PMID 34276694, 2021).
tendonitis (1 paper, 2023). "Changes in the MMP family during tendon healing were another important factor in the formation of adhesive texture, studies have shown that when tendonitis occurs, the activity of MMP2 and MMP9 would change." (PMID 36859314, 2023).
tenosynovial giant cell tumour (1 paper, 2023). "MMP9, SPP1, and TYROBP were identified as osteoclast-specific up-regulated genes of the tenosynovial giant cell tumour via bioinformatic analysis, which had a reasonable diagnostic efficiency and served as potential drug targets." (PMID 38017559, 2023).
tenosynovitis (1 paper, 2025). Inflammation of the synovial lining of a tendon sheath. "Leukocyte-rich PRP, used in some null studies, may increase pro-inflammatory cytokines (e.g., IL-1β, MMP-9), potentially exacerbating synovial inflammation in tenosynovitis." (PMID 41327174, 2025).
Theileria infection (1 paper, 2014). "Moreover, Theileria infection is known to induce AP-1-driven mmp9 expression via induction of the methyltransferase SMYD3 that promotes trimethylation of histone H3K4 (H3K4me3) at the mmp9 promoter." (PMID 25375322, 2014).
tick-borne encephalitis (1 paper, 2013). Tick-borne encephalitis is caused by an arbovirus of the Flaviviridae family (tick-borne encephalitis virus, TBEV), transmitted principally by the bite of the Ixodes ricinus tick. "MMP-9 levels of CSF samples obtained from tick-borne encephalitis patients." (PMID 24223711, 2013).
tongue tumor (1 paper, 2015).
Tracheomalacia (1 paper, 2024). "The incidence of stent-induced tracheomalacia and scar contracture were higher in Group B than that in Group A. IL-1RA, IL-8 and MMP9 may be involved in the development of complications after stentimplantation and peak value of group B movered backward." (PMID 38443931, 2024).
trichorhinophalangeal syndrome type I (1 paper, 2024). An autosomal dominant malformation syndrome caused by mutations in TRPS1 characterized by distinctive craniofacial and skeletal abnormalities. "Previous studies show that miR-222-3p has an oncogenic effect by regulating MMP2 (matrix metalloproteinaza), MMP9, TRPS1 (trichorhinophalangeal syndrome type 1), and CDKN1C/p57 (cyclin-dependent kinase inhibitor 1C)." (PMID 38542261, 2024).
tuberculous pleuritis (1 paper, 2018). "Chen and co-workers reported that TNF-α induced MMP-9 synthesis in human pleural mesothelial cells associated with Mycobacterium tuberculosis infection and that this process might be implicated in the pathogenesis of tuberculous pleuritis." (PMID 30544870, 2018).
tympanosclerosis (1 paper, 2025). The formation of dense connective tissue in the tympanic membrane that does not necessarily cause or lead to loss of hearing. "However, the 6-month follow-up period may be insufficient to investigate the predisposition of MMP-9 to tympanosclerosis." (PMID 40468054, 2025). "Compared with the inadequacy of animal models of tympanosclerosis to mimic the chronic process, our study reveals the late results of MMP-2 and MMP-9 in patients with tympanosclerosis." (PMID 40468054, 2025). "Our study differs from previous animal studies in that the low rate of staining of eardrum and middle ear mucosa samples with MMP-9 in tympanosclerosis." (PMID 40468054, 2025). "In our study, the increased MMP-2 and decreased MMP-9 staining rates in tympanosclerosis suggest that it represents the late stage of the disease and that the atrophied mucosa is no longer able to respond to further microbial invasion." (PMID 40468054, 2025). "In the tympanosclerosis animal model, in which the possible role of MMP-9 together with TGF-β1 was investigated, it was reported that TGF-β1 expression increased with the development of tympanosclerosis at 8 weeks, and MMP-9 expression increased slowly from 1 to 4 weeks and decreased at 6 weeks." (PMID 40468054, 2025). "According to the results of our study, it was thought that MMP-2 may play a role in the late and more sclerotic period of tympanosclerosis, and MMP-9 may play a role in the pre-tympanosclerosis period of COM." (PMID 40468054, 2025). "More long-term studies are needed to investigate the relationship between MMP-9 expression levels, which have been shown to be present in animal models of tympanosclerosis, in terms of the development of tympanosclerosis or disease recurrence on the basis of COM." (PMID 40468054, 2025). "However, more long-term studies are required to investigate the specific molecular mechanisms between MMP-2 and MMP-9 and determine the clinical utility of specific protease inhibitors in tympanosclerosis and other pathologic processes." (PMID 40468054, 2025). "High rates of MMP-2 staining in hard plaques compared with soft plaques suggest that MMP-2 represents the late period when the disease is more severe, and MMP-9 is less stained in both soft and hard plaques, suggesting that MMP-9 is suppressed in the late stage of tympanosclerosis." (PMID 40468054, 2025). "In conclusion, the relationship between MMP-2 and MMP-9 may play an important role in the pathogenesis of the development of tympanosclerosis against the background of chronic inflammation." (PMID 40468054, 2025). "In the literature, there are no studies investigating the presence of MMP-2 and MMP-9 together in sclerotic tissues and their effect on the disease in patients with tympanosclerosis." (PMID 40468054, 2025). "The fact that the preoperative air-bone conduction gap and postoperative 6th month airway mean values ​​were lower in the study groups stained with MMP-9 may indicate that MMP-9 is effective in the period when tympanosclerosis is not early or more widespread." (PMID 40468054, 2025).
type A aortic dissection (1 paper, 2025). "One example of this is one of the models that combined D-dimer, CRP, and MMP-9 to predict 1-year mortality in type A aortic dissection patients." (PMID 39910669, 2025).
Umbilical hernia (1 paper, 2020). Protrusion of abdominal contents through a defect in the abdominal wall musculature around the umbilicus. "In the present study, the MMP13 and MMP9 genes were 7.3 and 3.9 times less expressed in animals affected by umbilical hernia than in normal animals." (PMID 32379844, 2020).
undifferentiated endometrial carcinoma (1 paper, 2023). "MMP-9 expression in all types of cancers except grade 1 endometrioid and clear cell compared to proliferative endometrium was significantly higher (p < 0.05) and increased from proliferative to grade 2 endometrioid, grade 3 endometrioid, serous and undifferentiated endometrial carcinoma." (PMID 36945954, 2023).
ureteral carcinoma (1 paper, 2021). "The pathological analysis of MMP-9 in primary ureteral carcinoma showed that the expression of MMP-9 was significantly higher than that in normal tissues." (PMID 33430865, 2021).
uterine tumor (1 paper, 2018). "We investigated the expression of 11 genes selected for their importance as potential biomarkers of epithelial cells (CK19, MUC1, HER family), cervical uterine tumor cells (HPV16-E6), or for their involvement in tumor progression (uPA, MMP9, VEGF, VEGF-C)." (PMID 29774091, 2018).
Varicose veins (1 paper, 2025). Enlarged and tortuous veins. "Finally, the last markers analysed were two MMPs (MMP-6 and MMP-9) as several studies have shown increased MMPs levels in patients with varicose veins." (PMID 40507076, 2025).
vascular tumor (1 paper, 2020). "MMP-9 cleaves and activates antiangiogenic precursors angiostatin, endostatin, and tumstatin by its protease activity, which all have an inhibitory effect on tumor growth and vascular tumor density." (PMID 33126765, 2020).
venous insufficiency (1 paper, 2022). Impaired venous blood flow or venous return (venous stasis), usually caused by inadequate venous valves. "In previous studies, we found increased levels of MMP-9 and COL-III, affecting the structure of the placentas of women with venous insufficiency during pregnancy." (PMID 36012236, 2022).
vesicoureteral reflux (1 paper, 2020). Abnormal flow of urine from the urinary bladder back into the ureters. "Other authors suggested the usefulness of the measurement of urinary MMP-9 excretion and the urinary MMP-9/TIMP-1 ratio for the prediction of vesicoureteral reflux in neonates with antenatal HN." (PMID 32670438, 2020).
villous adenocarcinoma (1 paper, 2014). An adenocarcinoma characterized by the presence of a villous architectural pattern. "The MMP-2 gene showed significant overexpression in mucinous type tumors, and MMP-9 was overexpressed in villous adenocarcinoma histologic type tumors." (PMID 24737953, 2014). "The overexpression of the matrix extracellular genes ITGA-3 and ITGB-5 is associated with advanced stage tumors, and the genes MMP-2 and MMP-9 are overexpressed in mucinous and villous adenocarcinoma type tumors, respectively." (PMID 24737953, 2014).
viral pneumonia (1 paper, 2023). Inflammation of the lung parenchyma that is caused by a viral infection. "Neutrophils recruited in the lungs of patients with atypical viral pneumonia are a key source of matrix metalloproteinase 9 (MMP-9), which is a matrixin, a class of enzymes that belong to the zinc-metalloproteinase family involved in the degradation of the extracellular matrix." (PMID 37476705, 2023).
withdrawal syndrome (1 paper, 2019). "MMP-9 upregulation in the spinal cord has also been implicated in chronic opioid-induced dependence, tolerance, and withdrawal syndrome through possible neuronal activation and interaction with NMDA receptors (NR1 and NR2B) via integrin-β1 and nitric oxide pathways." (PMID 31239855, 2019). "YKS, acting via the inhibition of MMP-9, might provide a new candidate for the prevention and treatment of cancer pain as well as reduce opioid-induced unwanted side effects (such as opioid-induced hyperalgesia, dependence, tolerance, and withdrawal syndrome)." (PMID 31239855, 2019).
tumor (5,533 papers, 1994 to 2026). "Matrix metalloproteinase-9 (MMP-9) is a key protease involved in extracellular matrix remodeling and tumor progression in NF2-associated VS, making it an attractive molecular target for activity-based sensing." (PMID 41675655, 2026). "Matrix metalloproteinase (MMPs) such as MMP-2 and MMP-9 facilitate tumor progression and EMT-associated metastasis directly by degrading the basement membrane components, allowing cancer cells to invade into the surrounding." (PMID 41480643, 2026). "Conversely, in cancer, KLF9 has emerged as a tumor-suppressor by inhibiting NF-κB, repressing metastasis-associated genes like MMP9 through chromatin remodeling and direct interference with NF-κB transcriptional activity." (PMID 40860800, 2025). "An important effector molecule released by tumor‐associated neutrophils, but also other cell types in the tumor microenvironment, is MMP9." (PMID 40397803, 2025). "The factors implicated in cancer cell proliferation and tumor progression include NE, MMP-9, CG, histones, and DNA." (PMID 40365275, 2025). "The increased levels of MMP-2 and MMP-9 in breast cancer are associated with the development of metastasis, poor survival, and larger tumor size." (PMID 40332096, 2025). "Specifically, MMP2 (gelatinase A) and MMP9 (gelatinase B) are associated with tumor spread and cell invasion." (PMID 40391158, 2025). "MMP-2 and MMP-9 are enzymes that play a crucial role in extracellular matrix regulation and have been implicated in the process of tumor migration and invasion." (PMID 40940722, 2025). "Increased serum and tissue levels of MMP-9 have been associated with enhanced tumor aggressiveness and reduced patient survival rates." (PMID 40149289, 2025). "Dysregulation of MMP9 has been implicated in tumor invasion and metastasis, underscoring its pivotal role in driving cancer progression through extracellular matrix degradation and stromal remodeling." (PMID 40822022, 2025). "The close association between paucimannosylation, MMP9 expression, and tumor aggressiveness underscores the complexity of glycoproteome remodeling and highlights the potential of glycan-focused approaches to improve patient management." (PMID 41041068, 2025). "In the context of disease, MMP-9 isoften implicated in processes that involve tissue remodeling or cell migration, suchas in tumor metastasis." (PMID 40674570, 2025). "ZEB1 deficiency prevents P.g.-induced vimentin and MMP-9 upregulation, reducing tumor cell migration, indicating its crucial role in EMT." (PMID 40924302, 2025). "Previous studies have identified MMP9+ macrophages as terminally differentiated TAMs, which are associated with tumour progression." (PMID 40847563, 2025). "Specific MMPs, such as MMP-9, are upregulated and associated with enhanced tumor invasion and therapeutic resistance in GBM." (PMID 40019229, 2025). "A recent study has shown that CA’s inhibitory effects on MMP-2 and MMP-9 are linked to its ability to block NF-κB activation, thereby reducing tumor development and spread in hepatocellular carcinoma cancer cells (HCC)." (PMID 40563423, 2025). "The release of MMP-9 is associated with the promotion of tumor angiogenesis and plays an important role in extracellular matrix(ECM) remodeling and membrane protein cleavage." (PMID 40160822, 2025). "While MMP9 is often linked with promoting invasion and metastasis, it can also have beneficial effects, such as influencing the immune response, modulating the tumor microenvironment, and facilitating tissue repair." (PMID 40870889, 2025). "In stage II-III CRC, MMP-9 cleavable PNPs (MMP9-PNPs) target KRASG12D mutations by delivering mRNA vaccines specifically to MMP-9 rich invasive tumor regions." (PMID 40688030, 2025). "This system enables conditional antibody activation via tumor-associated protease cleavage (MMP-9), thereby restoring antigen binding selectively in a conditional manner." (PMID 41246356, 2025).
tumor (continued). "Further, overexpression of MMP-3, the endogenous activator of MMP-9, was associated with higher tumor grades." (PMID 40019229, 2025). "In fact, previous results have indicated that MMP-9 is implicated in tumor radio-resistance as well as tumor metastasis." (PMID 40805215, 2025). "It inhibits the EGF-induced activation of MMP-2 and MMP-9, which are implicated in extracellular remodeling and tumor invasion." (PMID 40728967, 2025). "The histone deacetylase inhibitor (HDAC) valproic acid downregulates MMP-2 and MMP-9 expression, reduces stem-cell-associated properties and tumor metastatic potential, and promotes the anaplastic redifferentiation of tumor cells." (PMID 40565017, 2025). "Meanwhile, studies have indicated that PTX can inadvertently activate nuclear factor-kappa B (NF-κB), leading to the upregulation of matrix metalloproteinase-9 (MMP-9), which is associated with increased tumor invasiveness and metastasis." (PMID 40871063, 2025). "NF-κB, a regulator of MMP-9 and a key transcription factor in cancer cells, has been implicated in tumor progression by regulating angiogenesis and inhibiting apoptosis, promoting tumor invasion and metastasis." (PMID 41181710, 2025). "Elevated levels of MMP-9 in tumor tissues from patients are associated with decreased survival and increased tumor invasiveness, which are reduced when MMP-9 is inhibited." (PMID 41573658, 2025). "MMPs in particular, MMP-2 and MMP-9—have been connected to increased tumour invasiveness and metastasis and are implicated in the destruction of the extracellular matrix." (PMID 40027232, 2025). "In contrast, ERα signaling is linked to increased tumor invasion via MMP9 production, activation of the CXCL12/CXCR4 pathway and the promotion of M2 macrophage polarization and infiltration." (PMID 40612952, 2025). "Elevated MMP-2 and MMP-9 levels in patient tissue samples, serum, or cerebrospinal fluid (CSF) have been associated with advanced tumor grades, an increased risk of recurrence, and lower overall survival." (PMID 40265458, 2025). "MMP9, a matrix metalloproteinase implicated in extracellular matrix remodelling, plays a pivotal role in promoting tumor invasion and metastatic dissemination." (PMID 41240165, 2025). "Matrix Metalloproteinases (MMPs), especially MMP-9, are associated with tumor progression and metastasis." (PMID 41273852, 2025). "This generates the L-CHEK2 splice variant, activating fibroblast-derived MMP9 secretion and thereby inhibiting tumor metastasis and chemoresistance." (PMID 41304936, 2025). "The CV extract also suppressed MMP-9, a matrix metalloproteinase associated with poor cancer prognosis due to its role in tumour growth and spread." (PMID 41150756, 2025). "Neutrophils recruited to tumor sites can differentiate into tumor-associated neutrophils (TANs), which secrete matrix metalloproteinase-9 (MMP-9) and VEGF, promoting extracellular matrix degradation, angiogenesis, and metastasis." (PMID 41383623, 2025). "This strategy enables conditional activation of antibodies via tumor microenvironment (TME)-associated proteases (e.g., MMP-9), minimizing systemic off-tumor binding." (PMID 41246356, 2025). "Matrix metalloproteinase-9 (MMP-9) is implicated in tumor progression and vascular diseases, contributing to angiogenesis, metastasis, and extracellular matrix degradation." (PMID 40284474, 2025). "Tumor-associated macrophages (TAMs), in particular, become pro-angiogenic, producing vascular-modulating enzymes like MMP9 and growth factors such as VEGF, CCL2, and CXCL8." (PMID 40647432, 2025). "Of more than 20 different types of MMPs, MMP-9 has been implicated in various pathological processes, including inflammation, tissue injury, repair processes, and tumor progression." (PMID 40117070, 2025). "The NET-associated enzymes NE and MMP-9 remodel laminin, reactivating dormant tumor cells and promoting metastasis." (PMID 40805288, 2025).